AFAP1L2 (actin filament associated protein 1 like 2)
Description:
May play a role in a signaling cascade by enhancing the kinase activity of SRC. Contributes to SRC-regulated transcription activation.
Synonyms: KIAA1914; XB130; FLJ14564; Em:AC005383.4; CTB-1144G6.4
Tractability: Antibody: its Gene Ontology location is reachable by antibodies, with high confidence.
Gene: Protein-coding gene on chromosome 10 (114,293,604 to 114,404,775, reverse strand). Ensembl gene ENSG00000169129.
Subcellular location: Cytoplasm
Subcellular location (Human Protein Atlas): Cytosol; Plasma membrane
Gene Ontology:
Molecular function: protein tyrosine kinase activator activity; SH2 domain binding; SH3 domain binding
Biological process: inflammatory response; positive regulation of DNA-templated transcription; positive regulation of epidermal growth factor receptor signaling pathway; positive regulation of interleukin-8 production; regulation of interleukin-6 production; regulation of mitotic cell cycle
Cellular component: cytoplasm; cytosol
Genetic constraint (gnomAD): Loss-of-function variants: 44 observed, 93.45 expected, observed/expected ratio (o/e) 0.47, 90% interval 0.37 to 0.61. The upper end of that interval is the gene's LOEUF score, 0.61, which puts it in group 2 of 6, group 1 being the genes least tolerant of losing a copy. Missense variants: 937 observed, 1,019.8 expected, observed/expected ratio (o/e) 0.92, 90% interval 0.87 to 0.97. Synonymous variants: 378 observed, 408.35 expected, observed/expected ratio (o/e) 0.93, 90% interval 0.85 to 1.01.
Homologues: Orthologues: chimpanzee AFAP1L2 (99% identical), macaque AFAP1L2 (98% identical), rabbit AFAP1L2 (87% identical), dog AFAP1L2 (87% identical), guinea pig AFAP1L2 (85% identical), mouse Afap1l2 (83% identical), rat Afap1l2 (83% identical), pig AFAP1L2 (82% identical), tropical clawed frog afap1l2 (58% identical), zebrafish afap1l2 (52% identical). Paralogues in human: AFAP1 (36% identical), AFAP1L1 (34% identical).
Diseases named in the same sentence as AFAP1L2 in open-access papers:
AFAP1L2 is named in the same sentence as 39 diseases in open-access papers, as found by Europe PMC text mining. Sharing a sentence is not in itself a finding about the gene and the disease. The quoted sentences say what the papers report.
breast carcinoma (5 papers, 2016 to 2023). "Although AFAP1L2 is also associated with tumor progression, such as prostate cancer, non-small cell lung cancer and breast cancer, AFAP1L2 acts as a tumor suppressor in carcinogen-induced skin tumorigenesis." (PMID 36631800, 2023). "AFAP1L2 has been reported to be associated with tumor progression or suppression in various cancers, including prostate cancer, non-small-cell lung cancer, breast cancer and carcinogen-induced skin tumorigenesis." (PMID 38066476, 2023). "The expression level of AFAP1L2, involved in signal transduction, has been described as a potential tumor marker in soft tissue tumors, while endonuclease-encoding ANKLE1, which plays a role in DNA damage and repair, has been suggested as a breast cancer marker." (PMID 35408779, 2022).
lung carcinoma (4 papers, 2012 to 2023). "Previous reports showed that silencing of AFAP1L2 in thyroid and lung cancer cells inhibits cell-cycle progression and survival." (PMID 37388918, 2023).
hepatocellular carcinoma (3 papers, 2014 to 2024). A malignant tumor that arises from hepatocytes. "Moreover, AFAP1L2-SRC-FUNDC1 pathway-dependent mitophagy has been demonstrated to be involved in mitigating sorafenib resistance in hepatocellular carcinoma cells." (PMID 39668821, 2024). "ART mitigates sorafenib resistance in hepatocellular carcinoma (HCC) patients by exacerbating AFAP1L2-SRC-FUNDC1 axis-dependent mitochondrial autophagy." (PMID 39525639, 2024).
congenital hypothyroidism (2 papers, 2022 to 2023). A thyroid hormone deficiency present from birth. "An animal study found that defects in AFAP1L2 can affect cellular polarity and cytoskeletal structure, resulting in epithelial function disorders like congenital hypothyroidism." (PMID 38146362, 2023).
amyotrophic lateral sclerosis (1 paper, 2021). Amyotrophic lateral sclerosis (ALS) is a neurodegenerative disease characterized by progressive muscular paralysis reflecting degeneration of motor neurons in the primary motor cortex, corticospinal tracts, brainstem and spinal cord. "AFAP1L2 (another gene identified based on AI analysis) showed differential expression in oligodendrocytes of the Amyotrophic lateral sclerosis murine model." (PMID 34260616, 2021).
autism (1 paper, 2021). Persistent deficits in social interaction and communication and interaction as well as a markedly restricted repertoire of activity and interest as well as repetitive patterns of behavior. "Four genes cg23920016 (NOS1AP), cg24274662 (MOSPD1), cg26017408 (AFAP1L2) and cg16930349 (GRIPAP1) identified based on predictive ability for autism using AI analysis." (PMID 34260616, 2021).
COVID-19 (1 paper, 2025). A disease caused by infection with severe acute respiratory syndrome coronavirus 2. "Cg17126990 (annotated to AFAP1L2) and cg25483596 (annotated to PC) were the common CpG sites identified to be differentially methylated across the different study approaches, thus suggesting their relevance in the aftermath of COVID-19." (PMID 40251596, 2025).
diabetes (1 paper, 2022). "Further correlation analysis indicated the key molecules involved in PI3K-AKT signaling pathway, such as AKT1, AKT2, PIK3R1, and PIK3R2, showed significant positive correlations with AFAP1L2, and in which AKT1 also showed elevated expression in patients without diabetes history." (PMID 36434634, 2022).
leukemia (1 paper, 2013). A malignant (clonal) hematologic disorder, involving hematopoietic stem cells and characterized by the presence of primitive or atypical myeloid or lymphoid cells in the bone marrow and the blood. "Interestingly, DHH-RHEBL1-positive patients showed higher expression of several genes known to be associated with leukemia occurrence and/or tumor progression, such as FLT3, BEX1, MUC4 and AFAP1L2." (PMID 24127550, 2013).
liver cancer (1 paper, 2025). An epithelial or non-epithelial malignant neoplasm that arises from the liver. "In the context of liver cancer, artemisinin has been demonstrated to reduce the protein expression of actin filament associated protein 1-like 2 (AFAP1L2) and reverses sorafenib resistance in specific liver cancer cell lines (Hep G2, Hep3B, MHCC-97 H, and Huh-7)." (PMID 40490812, 2025).
melanoma (1 paper, 2021). A malignant, usually aggressive tumor composed of atypical, neoplastic melanocytes. "It has, however, been shown that at least one SNP pair at the TERF1 and the AFAP1L2 loci does interact to affect risk of melanoma." (PMID 34903281, 2021).
uterine leiomyosarcoma (1 paper, 2023). "In addition, BOK, NAALADL1, and AFAP1L2 were identified as genes with MSS values greater than 5 in uterine leiomyosarcoma samples." (PMID 38066476, 2023). "Specifically, genes such as PGR, TRIM22, BOK, NAALADL1, AFAP1L2, and ESR1 showed MSS values greater than 5 in uterine leiomyosarcoma samples." (PMID 38066476, 2023).
vesicoureteral reflux (1 paper, 2025). Abnormal flow of urine from the urinary bladder back into the ureters. "AFAP1L2 enables SH3 domain binding activity and protein tyrosine kinase activator activity and is involved in the positive regulation of the epidermal growth factor receptor signaling pathway, associated with vesicoureteral reflux and cartilage cancer." (PMID 40251596, 2025).
tumor (16 papers, 2011 to 2023). "An intracellular cytokine staining of tumor-infiltrating T cells showed that the percentage of Afap1l2-edited OT-I T cells producing TNFα and IFN-γ was twice as high as in controls." (PMID 37388918, 2023). "When we followed B16.OVA tumor sizes over time, we found that Afap1l2-edited OT-I T cells mounted a superior anti-tumor response than control T cells." (PMID 37388918, 2023). "A further comparison with blood NK cells revealed that only the potential HCC marker protein AKR1B10, which was also enriched in TAMs, and AFAP1L2, a cytosolic signaling scaffold protein, were specifically upregulated in tumor-infiltrating NK cells." (PMID 37388918, 2023). "MC38-OVA tumor cells were subcutaneously injected into Cd3e−/− mice, and after 5 days, either control or Afap1l2-edited OT-I T cells were adoptively transferred." (PMID 37388918, 2023). "AFAP1L2 belongs to the actin filament-associated protein (AFAP) family, which is known affect tumor cell proliferation, invasion, epithelial-mesenchymal transition and participate in tumor progression." (PMID 38066476, 2023). "Under these conditions, Afap1l2-edited OT-I T cells had a superior anti-tumor activity than control OT-I T cells." (PMID 37388918, 2023). "Taken together, these data indicate that Afap1l2 knockout increases both the quantity and potency of the anti-tumor T cell response." (PMID 37388918, 2023). "An additional therapeutic application of our findings would be to genetically ablate AFAP1L2 in CAR T cells to improve their anti-tumor function." (PMID 37388918, 2023). "In summary, we found that chronically stimulated CD8+ T cells induce AFAP1L2, which when ablated improves their anti-tumor functions." (PMID 37388918, 2023). "We additionally treated mice with PD-L1 blocking antibodies and found that PD-L1 blockade combined with ablation of Afap1l2 in T cells synergistically reduced tumor growth and significantly increased the survival of mice." (PMID 37388918, 2023). "Taken together, AFAP1L2 is upregulated in activated, tumor-infiltrating NK cells." (PMID 37388918, 2023). "Since AFAP1L2 is only expressed in T cells upon repeated stimulation, it could serve as a specific target to exclusively reinvigorate chronically stimulated T cells at the tumor site." (PMID 37388918, 2023). "AFAP1L2 was expressed specifically in chronically stimulated CD8+ T cells in tumors, and its genetic ablation improved anti-tumor activity." (PMID 37388918, 2023). "A differential abundance analysis between proteomes of NK cells isolated from liver and tumor tissues identified four proteins that were increased in tumor NK cells (Log2 fold change > 2; p value < 0.01): AKR1B10, GLUL, IGHMBP2, and AFAP1L2." (PMID 37388918, 2023). "They identified significant phenotype alterations in tumor-infiltrating immune cells, including SGPL1 upregulation in macrophages and AFAP1L2 in T cells." (PMID 37388918, 2023). "Genetic ablation of Afap1l2 in murine CD8+ T cells improved their survival and anti-tumor activity and had synergistic effects with PD-L1 blocking antibodies in the clearance of tumors." (PMID 37388918, 2023). "Ablation of AFAP1L2 in CD8+ T cells increased their viability upon repeated stimulation and enhanced their anti-tumor activity synergistically with PD-L1 blockade in mouse models." (PMID 37388918, 2023). "Lastly, in CR-TNBC patient P942, the baseline PDX tumor (BTY14) had high phosphorylation on the shared pTyr sites of SRC, FYN, LCK, YES1, and FGR as well as SFK substrates such as tensin, SHIP-1 (INPP5D), AFAP1L2, paxillin, and PTK2." (PMID 36077757, 2022). "Because tumor-specific CD8+ TILs are chronically stimulated at the tumor site, we hypothesized that TOX, LMCD1, and AFAP1L2 might be induced upon chronic stimulation." (PMID 37388918, 2023).
tumor (continued). "However, TOX, LMCD1, and AFAP1L2 were either not detected or only at very low levels, suggesting that their presence in tumor-infiltrating T cells was not a consequence of the canonical T cell activation program." (PMID 37388918, 2023). "Thus, AFAP1L2 does not impact proliferation but promotes cell death of chronically stimulated T cells and may therefore have a negative effect on tumor control." (PMID 37388918, 2023).
cancer (15 papers, 2011 to 2023). A tumor composed of atypical neoplastic, often pleomorphic cells that invade other tissues. "Furthermore, other genes, such as MUC4 and AFAP1L2, associated with different human cancers, resulted overexpressed in DHH-RHEBL1-positive patients." (PMID 24127550, 2013). "In all cancer types, AFAP1L2 was present in clusters of PD-1+ CD8+ T cells that express exhaustion markers such as LAG3, TIM-3, and CD39." (PMID 37388918, 2023). "Collectively, these data indicate that AFAP1L2 is induced in repeatedly stimulated CD8+ T cells across different cancer types." (PMID 37388918, 2023). "This suggests that AFAP1L2 is a potential target for T cell-based cancer immunotherapies to treat patients with HCC and other types of tumors." (PMID 37388918, 2023). "When AFAP1L2 is translocated into the thyroid cell nucleus, it can promote cell cycle and induce cancer cells to inhibit apoptosis in early-stage PTC." (PMID 31126066, 2019). "Thus, systemic targeting of AFAP1L2 would potentially enhance the activity of chronically stimulated T cells and directly inhibit the growth of cancer cells." (PMID 37388918, 2023). "Notably, the functions of AFAP1L2 are cell type specific since it curtails the survival of chronically stimulated T cells but has the opposite effect in cancer cells." (PMID 37388918, 2023).
AFAP1L2 also shares sentences with these, for which no sentence is quoted: thyroid cancer (10 papers); gastric cancer (6); esophageal cancer (3); esophageal squamous cell carcinoma (3); prostate carcinoma (3); thyroid (3); colorectal cancer (2); deafness (2); lymph node metastasis (2); non-small cell lung carcinoma (2); pancreatic cancer (2); soft tissue tumors (2); colon cancers (1); endocrine cancers (1); epilepsy (1); glomerular disease (1); hypothyroidism (1); lung adenocarcinoma (1); multinodular goiter (1); pancreatic ductal adenocarcinoma (1); papillary thyroid carcinoma (1); salivary gland carcinoma (1); thyroid follicular carcinoma (1); thyroid tumor (1).